UBE2T (ubiquitin conjugating enzyme E2 T)
Diseases named in the same sentence as UBE2T in open-access papers (continued):
Sharing a sentence is not in itself a finding about the gene and the disease.
breast carcinoma (31 papers, 2015 to 2025). "In the present study, immune cell infiltration analyses showed that Th1 was negatively associated with ANLN in all types of breast cancer, whereas it was positively associated with UBE2T in luminal A breast cancer." (PMID 35578283, 2022). "ANLN and UBE2T upregulation was associated with the prevalence of Th1 and Th2 cells, shifting the Th1/Th2 balance to Th2 in Basal and Luminal-B breast cancers, which indicates a poor prognosis (P < 0.05)." (PMID 35578283, 2022). "Analysis of the C Bioportal database showed that UBE2T is amplified in approximately 12% of breast cancer tumors and is associated with adverse outcomes in basal-like and luminal breast cancer patients." (PMID 35578283, 2022). "Upregulation of the expression of ANLN and UBE2T is associated with a worse prognosis of breast cancer." (PMID 35578283, 2022). "Th2 was significantly positively associated with ANLN in TNBC and luminal B breast cancer and significantly positively associated with UBE2T in all subtypes of breast cancer." (PMID 35578283, 2022). "Taken together, these findings indicate that the expression of ANLN and UBE2T is associated with immune cell infiltration and the immunosuppressive microenvironment in different subtypes of breast cancer." (PMID 35578283, 2022). "Prior studies have published that UBE2T was overexpressed and linked with undesirable outcome in breast cancer patients." (PMID 34787051, 2021). "This study provided insights into understanding the regulatory mechanism underlying miR-543 and UBE2T in the development of breast cancer." (PMID 34787051, 2021). "The independent data and qRT-PCR showed that they were significantly up-expressed and associated with poor outcome in breast cancer except UBE2T and FAM64A." (PMID 33313822, 2021). "While IFI6 overexpression can reverse the DNA replication stress and growth inhibition caused by UBE2T knockdown, it may also promote breast cancer cell growth through non-UBE2T-dependent pathways, influencing the multifaceted tumor phenotype." (PMID 39791716, 2024). "Thus, the UBE2T→IFI6→DNA replication stress→apoptosis pathway represents a potential new therapeutic target for breast cancer cases associated with high UBE2T expression levels." (PMID 36338541, 2022). "Finally, a loss-of-function germline mutation in UBE2T was detected in a high-risk breast cancer patient with wild-type BRCA1/2." (PMID 26085575, 2015). "However, different immune-related patterns may indicate different mechanisms underlying the function of ANLN and UBE2T in different breast cancer subtypes." (PMID 35578283, 2022). "We next examined whether UBE2T overexpression was associated with prognosis and found that breast cancer samples with higher UBE2T expression levels were associated with shorter on relapse-free survival and (RFS) and shorter overall survival (OS) among breast cancer patients." (PMID 36338541, 2022). "Finally, the detection of a germline mutation in 1 of 450 high-risk breast cancer patients with normal BRCA1/2 suggests that UBE2T also could be a very rare cancer susceptibility gene." (PMID 26085575, 2015). "Previous studies have shown that UBE2T is involved in the development of various tumors such as breast cancer and liver cancer, but research on the role of UBE2T in UCEC is limited." (PMID 39367897, 2025). "In recent years, UBE2T has been found to participate in the development of cancers such as liver cancer, breast cancer, and others." (PMID 39367897, 2025). "UBE2T is recognized as an oncogene in breast cancer, with studies linking high UBE2T expression to tumorigenesis, progression, and poor prognosis." (PMID 39791716, 2024). "In this study, we found that UBE2T is overexpressed in breast cancer and that UBE2T overexpression predicts poor prognosis." (PMID 36338541, 2022). "We also found that IFI6 was one of the most significantly expressed genes next to UBE2T in breast cancer cell lines." (PMID 36338541, 2022).
breast carcinoma (continued). "After UBE2T knockdown was validated in these breast cancer cell lines via qPCR and immunoblotting, these cells were tested for their abilities to grow in an anchorage-independent manner using soft-agar assays." (PMID 36338541, 2022). "Mechanistically, UBE2T inhibition in breast cancer cells suppresses interferon alpha–inducible protein 6 (IFI6) expression, resulting in DNA replication stress, cell cycle arrest, and apoptosis induction." (PMID 36338541, 2022). "RNA sequencing analysis identified interferon alpha–inducible protein 6 (IFI6) as a key downstream mediator of UBE2T function in breast cancer cells." (PMID 36338541, 2022). "Here, we show that ubiquitin-conjugating enzyme E2T (UBE2T) is overexpressed in patient-derived breast cancer samples, and UBE2T overexpression predicts poor prognosis." (PMID 36338541, 2022). "For example, UBE2T promoted the proliferation of breast cancer cells via ubiquitinating and downregulating BRCA1." (PMID 35169125, 2022). "We analyzed publicly available breast cancer datasets and found that UBE2T mRNA was significantly overexpressed in breast cancer samples due to both gene amplification and transcriptional upregulation [TCGA breast, Curtis breast, and Zhao breast datasets]." (PMID 36338541, 2022). "Collectively, these studies identify UBE2T as a facilitator of breast cancer tumor growth through the suppression of IFI6 expression, DNA replication stress, and apoptosis induction." (PMID 36338541, 2022). "To confirm UBE2T overexpression at the protein level, we analyzed a breast cancer TMA (#BC081120f), which included 100 cases of invasive breast cancer tissue and 10 adjacent normal breast tissues." (PMID 36338541, 2022). "We next attempted to determine the mechanism driving UBE2T overexpression in breast cancer cells to promote cell growth." (PMID 36338541, 2022). "We used two sequence-independent shRNAs to knock down UBE2T expression in the luminal A breast cancer cell lines MCF7 and T47D." (PMID 36338541, 2022). "Ten hub-key genes were identified, and survival analysis showed that UBE2T and ANLN were upregulated in breast cancer and their upregulation was associated with a poor prognosis." (PMID 35578283, 2022). "We show that UBE2T knockdown increases the sensitivity of breast cancer cells to DNA replication stress inducers." (PMID 36338541, 2022). "We found that hydroxyurea and aphidicolin induced more potent inhibitory effects on the growth of breast cancer cells expressing UBE2T shRNA than on the growth of cells expressing NS shRNA, and these effects increased in a concentration-dependent manner." (PMID 36338541, 2022). "Paraffin samples were used to examine the expression of ANLN and UBE2T in breast cancer tissues by immunohistochemistry, and three samples of each subtype of breast cancer were included." (PMID 35578283, 2022). "Taken together, our study identifies UBE2T as a facilitator of breast cancer tumor growth and provide a rationale for targeting UBE2T for breast cancer therapies." (PMID 36338541, 2022). "The results confirmed that the expression of ANLN and UBE2T was detectable in all types of breast cancer." (PMID 35578283, 2022). "We demonstrate that the transcription factor AP-2 alpha (TFAP2A) is necessary for the overexpression of UBE2T in breast cancer cells, and UBE2T inhibition suppresses breast cancer tumor growth in cell culture and in mice." (PMID 36338541, 2022). "Collectively, these results demonstrated that the transcription factor TFAP2A is overexpressed in breast cancer cells and is necessary for the transcriptional overexpression of UBE2T." (PMID 36338541, 2022). "Based on these results, we next investigated the role of UBE2T-regulated IFI6 expression in breast cancer cell growth." (PMID 36338541, 2022). "Numerous studies have shown that UBE2T, as an oncogene, plays a role in a variety of tumours, including breast cancer, liver cancer, lung cancer, prostate cancer, kidney cancer, bladder cancer, glioma, etc.." (PMID 36088429, 2022).
breast carcinoma (continued). "We treated NS shRNA expressing and UBE2T shRNA expressing breast cancer cells with the DNA replication stress–inducing agents’ hydroxyurea and aphidicolin and measured cell viability using the MTT assay." (PMID 36338541, 2022). "We further showed that IFI6 overexpression effectively reverses DNA replication stress and the inhibition of colony-forming growth induced by UBE2T knockdown in breast cancer cells, partially restoring breast cancer cell proliferation." (PMID 36338541, 2022). "We identified that UBE2T regulates DNA replication stress in breast cancer cells by stimulating the expression of IFI6, suppressing DNA replication stress, cell cycle arrest, and apoptosis induction." (PMID 36338541, 2022). "Collectively, these results demonstrate that UBE2T is overexpressed in breast cancer and predicts poor prognosis." (PMID 36338541, 2022). "Collectively, these results show that UBE2T knockdown leads to cell cycle arrest and apoptosis induction, which inhibit breast cancer cell growth." (PMID 36338541, 2022). "This indicates that the expression of ANLN and UBE2T affects immune cells in different subtypes of breast cancer." (PMID 35578283, 2022). "We analyzed publicly available breast cancer datasets and found that, similar to UBE2T mRNA, IFI6 mRNA was significantly overexpressed in breast cancer samples relative to normal breast samples." (PMID 36338541, 2022). "In this study, we found that UBE2T is overexpressed at both the mRNA and protein levels in patient-derived breast cancer samples, and UBE2T overexpression predicted poor survival among patients with breast cancer." (PMID 36338541, 2022). "TFAP2A knockdown also inhibited the abilities of breast cancer cells to grow in an anchorage-independent manner in soft-agar assays, mimicking the growth inhibitory phenotype observed with UBE2T inhibition in breast cancer cells." (PMID 36338541, 2022). "Guided by these results, we also examined DNA replication stress in UBE2T shRNA expressing breast cancer cells and found that inhibition of UBE2T expression also led to the activation of DNA replication stress." (PMID 36338541, 2022). "Our results showed that TFAP2A knockdown reduced UBE2T expression at the mRNA and protein levels in breast cancer cells." (PMID 36338541, 2022). "We found that UBE2T knockdown in breast cancer cells significantly reduced their abilities to form colonies in soft agar." (PMID 36338541, 2022). "Subsequently, we carried out Spearman rank correlation analysis of UBE2T and breast cancer genes (BRCA1, BRCA2)." (PMID 36088429, 2022). "The expression of ANLN and UBE2T in all types of breast cancer was confirmed by immunohistochemistry." (PMID 35578283, 2022). "Based on these results, miR-543 exhibited reduced expression in breast cancer tissues and cell lines, whereas UBE2T exhibited high levels." (PMID 34787051, 2021). "Here, the purpose of this study was to explore the relationship between UBE2T and miR-543 and their regulation pathway in breast cancer progression." (PMID 34787051, 2021). "The prognostic values of UBE2T have been studied in lung and breast cancer, HCC, and multiple myeloma." (PMID 34257599, 2021). "Later, the cancer-inducing role of UBE2T was demonstrated in multiple types of malignancies, including breast cancer." (PMID 34787051, 2021). "Similar to the confirmation of the action of miR-543 in cell migration and invasion in breast cancer cells, we also explored the role of UBE2T through rescued experiments." (PMID 34787051, 2021). "Taken together, miR-543 repressed UBE2T to inhibit cell viability and proliferation in breast cancer cells." (PMID 34787051, 2021). "Our results implied that miR-543 had reduced expression in breast cancer tissues, whereas its targeted gene UBE2T exhibited higher expression in breast cancer tissues." (PMID 34787051, 2021).
breast carcinoma (continued). "UBE2T was also observed to promote breast cancer cell proliferation by specifically regulating the ubiquitination-mediated degradation of breast cancer-associated protein 1 (BRCAl)." (PMID 34257599, 2021). "In this study, our experimental verification confirmed the high UBE2T expression in breast cancer and demonstrated its significant function in the development and progression of breast cancer, which was regulated and restored with the introduction of miR-543." (PMID 34787051, 2021). "Compared with the Bio-NC, the enrichment of UBE2T was increased in the Bio-miR-543 group, which suggested that miR-543 directly targeted UBE2T in breast cancer cells." (PMID 34787051, 2021). "Collectively, these results verified that miR-543 directly targeted UBE2T and suppressed UBE2T expression in breast cancer cells." (PMID 34787051, 2021). "Overall, miR-543 alleviated breast cancer progression and malignancy through the regulation of UBE2T." (PMID 34787051, 2021). "The results allowed us to demonstrate that miR-543 works as an anti-tumor regulator in breast cancer cells by downregulating the expression of UBE2T, whose high expression can enhance the proliferation and malignancy of breast cancer." (PMID 34787051, 2021). "At present, UBE2T has been reported to be upregulated in lung cancer, breast cancer, prostate cancer, nasopharyngeal carcinoma and HCC." (PMID 31969492, 2020). "Our study showed that ASPM, INHBA, NUF2, ORC6, UBE2T and PKMYT1 are associated with cell proliferation, and the expressions of these genes were also elevated in our breast cancer tissue transcriptome." (PMID 31182966, 2019). "Of note, although there are data describing the biological role of UBE2T and DTL in breast cancer, their association with poor outcome in lung adenocarcinomas has not been described before." (PMID 29235520, 2017). "Two genes, the ubiquitin-conjugating enzyme E2T (UBE2T) and the denticleless protein homolog (DTL) were overexpressed and linked with detrimental outcome in basal-like and luminal breast cancer patients." (PMID 29235520, 2017). "UBE2T is transcriptionally up-regulated with increased protein levels observed in breast cancers of different histological subtypes, including papillotubular, solid tubular, and scirrhous carcinoma." (PMID 27729585, 2016). "Previous studies have revealed that UBE2T promotes colony formation in NIH3T3 cells and that knockdown of endogenous UBE2T inhibited proliferation of T47D and BT-20 breast cancer cell lines." (PMID 26943030, 2016). "Perhaps the most convincing evidence is that downregulation of BRCA1 by UBE2T in breast cancer significantly promoted proliferation and tumor growth of breast cancer cells." (PMID 26308072, 2015). "We ectopically expressed IFI6 in breast cancer cells expressing UBE2T shRNA and tested whether IFI6 overexpression restored normal DNA replication by preventing DNA replication stress and apoptosis." (PMID 36338541, 2022). "Because UBE2T is overexpressed in breast cancer, we rationalized that UBE2T might be involved in breast cancer tumor growth." (PMID 36338541, 2022). "Analysis of the GSEA50567, GSEA65194, and GSEA43358 datasets showed that ANLN and UBE2T expression was higher in breast cancer than in normal tissues (P < 0.05) and higher in TNBC and HER2 overexpressing subtypes than in luminal A and luminal B subtypes (P < 0.05)." (PMID 35578283, 2022). "Similarly, UBE2T promotes the proliferation, invasion, and glycolysis of breast cancer cells by regulating the PI3K/AKT signaling pathway." (PMID 35578283, 2022). "Based on these results, we examined whether UBE2T knockdown also inhibits breast cancer tumor growth using an in vivo xenograft mouse model of breast cancer." (PMID 36338541, 2022). "The expression of ANLN and UBE2T influence immune cells in different subtypes of breast cancer." (PMID 35578283, 2022).
breast carcinoma (continued). "Some studies have found that the overexpression of UBE2T may promote the occurrence of breast cancer during the whole process of BRCA1 downregulation." (PMID 36088429, 2022). "However, only four of these transcription factors were significantly co-overexpressed with UBE2T in patient-derived breast cancer samples." (PMID 36338541, 2022). "ANLN and UBE2T are potential biomarkers for predicting the prognosis of breast cancer." (PMID 35578283, 2022). "ANLN and UBE2T are potential prognostic biomarkers and novel therapeutic targets in breast cancer." (PMID 35578283, 2022). "Based on these findings, we examined whether UBE2T is overexpressed in breast cancer and whether its overexpression predicts poor prognosis." (PMID 36338541, 2022). "Based on these results, we performed experiments to determine whether IFI6 acts as a downstream mediator of UBE2T-induced tumor growth in breast cancer." (PMID 36338541, 2022). "To more comprehensively determine the mechanisms through which UBE2T contributes to breast cancer growth and identify new mediators of UBE2T function, we performed transcriptome-wide mRNA expression profiling of breast cancer cell lines (MCF7 and T47D) expressing either UBE2T or NS shRNA." (PMID 36338541, 2022). "Elucidating the role of ANLN and UBE2T in breast cancer is thus important." (PMID 35578283, 2022). "In addition, overexpression of UBE2C and UBE2T, which are ubiquitin conjugating enzymes, are known for promoting cell proliferation in breast cancer." (PMID 36077657, 2022). "Therefore, cell cycle arrest in the G1 phase, such as that observed in UBE2T shRNA expressing breast cancer cells, prevents progression to the S and G2 phases and inhibits cell division." (PMID 36338541, 2022). "In breast cancer, UBE2T promoted tumorigenesis via the ubiquitin-mediated degradation of BRCA1." (PMID 36357897, 2022). "We performed IHC analysis, which showed the significant elevation of UBE2T protein expression in the large majority of patient-derived breast cancer samples relative to normal breast tissue samples, consistent with gene amplification and transcriptional upregulation." (PMID 36338541, 2022). "However, the ectopic expression of IFI6 in UBE2T-knockdown cells prevented DNA replication stress and apoptosis and partly restored breast cancer cell growth." (PMID 36338541, 2022). "The transcription factor TFAP2A regulates UBE2T expression in breast cancer cells, and previous study has shown that TFAP2A regulates the expression of several genes that promote cancer growth and contribute to determining anticancer therapy resistance and sensitivity." (PMID 36338541, 2022). "We found that IFI6 knockdown in breast cancer cells resulted in significant reductions in the abilities of these cells to form colonies in soft agar, mimicking the growth inhibitory phenotype observed in UBE2T-knockdown cells." (PMID 36338541, 2022). "Some studies showed that the overexpression of UBE2T could promote the proliferation of breast cancer cells by repressing BRCA1 expression." (PMID 36168930, 2022). "We noticed that UBE2T was once reported to be a proliferation promoter in breast cancer, but the effects of UBE2T on other cell phenotypes have not been reported, nor has whether UBE2T can be regulated by miRNAs." (PMID 34787051, 2021). "Because miR-543 was able to target UBE2T in breast cancer cells, confirming whether miR-543 could exert a function interacting with UBE2T was conducted." (PMID 34787051, 2021). "However, despite the mechanical demonstration of the miR-543/UBE2T axis in the breast cancer process in this study, the effect of miR-543 and UBE2T is lacking in vitro verification." (PMID 34787051, 2021). "Therefore, it is reasonable to regard UBE2T as a promising drug target for patients with breast cancer." (PMID 34787051, 2021). "However, we demonstrated that miR-543 inhibited the malignant development of breast cancer by targeting UBE2T through the ERK/MARK signaling pathway." (PMID 34787051, 2021).